ESR1 (estrogen receptor 1)
Diseases named in the same sentence as ESR1 in open-access papers (continued):
Sharing a sentence is not in itself a finding about the gene and the disease.
breast cancer (continued). "The advent of ddPCR facilitates routine investigations of ESR1 mutations as a potential monitoring biomarker for patients with breast cancer treated with endocrine therapy." (PMID 33233830, 2020). "Several molecular methods have been developed and evaluated for these ESR1 mutations that are strongly involved in breast cancer development and progression." (PMID 33233830, 2020). "It has been recognized that estrogen receptors alpha (ERα), encoded by ESR1, are positively expressed in about 65% of breast cancer subjects." (PMID 33292226, 2020). "In particular, ESR1 was more frequently mutated in metastatic breast cancer than in early breast cancer and has been identified both as a driver and as a metastatic gene." (PMID 33233830, 2020). "In summary, applied molecular methodologies for identifying ESR1 mutations, one of the major causes of resistance to endocrine therapy in patients with advanced breast cancer, were reviewed." (PMID 33233830, 2020). "In the context of OSM/OSMR signaling, high levels of OSM and OSMR mRNA expression were associated with low expression of ESR1 (ER) and ER-regulated genes in a breast cancer gene expression data set." (PMID 32023849, 2020). "ERα, the protein encoded by ESR1, is well known to be an independent prognostic factor in breast cancer, and thus is a target of endocrine therapy." (PMID 33291081, 2020). "Some of the listed genes already have functional data linking breast cancer CCVs and somatic point mutations to altered target gene expression, including ESR1, FGFR2, and MAP3K1." (PMID 31910858, 2020). "In a recent study, the authors identified the 6q25 region, where ESR1 is located, as associated with breast cancer in U.S. Latinas, Mexican, and Colombian patients." (PMID 33126731, 2020). "For example, estrogen receptor 1 (ESR1) mutation detected in the ctDNA of breast cancer (BC) patients pre-treated with aromatase inhibitors correlated with inferior treatment outcome on exemestane, but not on fulvestrant." (PMID 33033274, 2020). "While the discovery of ESR1 mutations offers valuable insights into the evolution of breast tumors under the selective pressure of therapy, only a fraction of breast cancer patients with endocrine-resistant tumors harbors these mutations." (PMID 32650428, 2020). "ESR1 mutations of breast cancer are often reported after aromatase inhibitor and/or tamoxifen therapy." (PMID 33004031, 2020). "This study has gone some way toward enhancing our understanding of the underlying molecular mechanism of ESR1-mediated progression of ERα positive breast cancer and this research will serve as a base for future studies in this field." (PMID 32500028, 2020). "Molecular assays and main characteristics of the studies for advanced breast cancer with ESR1 mutations." (PMID 33233830, 2020). "ESR1 is the estrogen-receptor gene, common in primary breast cancers, whose mutation is indicative of resistance to anti-estrogen therapies." (PMID 32127627, 2020). "Promoter methylation of ESR1 in breast cancer was related to worse overall survival and associated with a lack of response to endocrine treatment." (PMID 32536040, 2020). "The selection of ESR1 mutations can occur not only in metastatic disease, but also in primary disease, as supported by a recent study investigating ESR1 mutations in primary breast cancers that were treated with AIs for more than six months." (PMID 32210163, 2020). "Activating mutations in ESR1 acquired in response to aromatase inhibitor (AI) treatment have also emerged as an important genomic marker in breast cancer, with the ability to predict response to subsequent endocrine treatments." (PMID 33001984, 2020). "SNPs rs12662670, rs2234693, rs2046210, rs3734805, and rs827421 in ESR1 were widely studied of their associations with breast cancer risk." (PMID 32150843, 2020).
breast cancer (continued). "The included studies were mainly based on three meta-analyses for ESR1 mutations in patients with breast cancer with resistance to endocrine therapy." (PMID 33233830, 2020). "The mutations in ESR1 are mainly observed in breast cancer patients who progress on AI therapy, but less frequently in patients who have not received AI for metastastic disease." (PMID 32210163, 2020). "To test the prevalence of ESR1 mutations, in the context of local recurrence, we assembled a cohort of 41 patients who experienced at least 1 local or loco-regional HR+ breast cancer recurrence." (PMID 32014063, 2020). "One study reporting ESR1 mutations in bone metastases from breast cancer adopted NGS and ddPCR simultaneously." (PMID 33233830, 2020). "Clinically relevant ESR1 mutations are prevalent in newly diagnosed metastatic and local recurrence of endocrine-treated breast cancer." (PMID 32014063, 2020). "Twenty-two included studies were from three recently published systematic reviews and meta-analyses reporting ESR1 mutations in advanced breast cancers with resistance to endocrine therapy." (PMID 33233830, 2020). "In breast cancer, ER, encoded by oestrogen receptor alpha gene (ESR1), is commonly deregulated by gene amplification, point mutations and genetic fusion, leading to enhanced cancer invasion and metastasis." (PMID 32372224, 2020). "In a population of 21 patients with recurrent breast cancer under adjuvant hormone therapy, ESR1 mutations were observed in 19% of patients, while using digital droplet PCR technique on plasma DNA samples." (PMID 32210163, 2020). "Results from other studies have identified ESR1 amplification in benign and early-stage breast cancer and is associated with endocrine therapy resistance." (PMID 31106278, 2019). "The results obtained in monoculture mirror those obtained in our previous cell autonomous studies with another breast cancer parental cell line, T47D, edited to express the same two ESR1 LBD mutations." (PMID 31171849, 2019). "This review covers both pre-clinical and clinical evidence on the spectrum of ESR1 alterations including amplification, point mutations, and genomic rearrangement events driving treatment resistance and metastatic potential of ER+ breast cancer." (PMID 31106278, 2019). "The amplification of estrogen receptor alpha (ERα) encoded by the ESR1 gene has been described as having a prognostic role in breast cancer patients." (PMID 30995757, 2019). "Remarkably, several ESR1 point mutations identified in acquired resistant breast cancer occur in ER ligand binding domain (LBD), just a few amino acids within or near the helix 12 region of the LBD." (PMID 31815253, 2019). "AZD9496 has been shown to potently antagonise and degrade ER in preclinical studies with MCF7 ER+ breast cancer cell line and xenograft models as well as in patient-derived xenografts harbouring an ESR1 mutation." (PMID 30555156, 2019). "Our overall goal was to determine the relationships among a relevant and controllable TME of human breast cancer liver metastasis and tumor phenotypes conferred by clinically observed ESR1 mutations." (PMID 31171849, 2019). "AR and ESR1 in particular are more prevalent, with putative driver mutations in 44% of prostate and 16% of breast cancers, respectively." (PMID 31645765, 2019). "No other investigated polymorphism showed a significant association with breast cancer itself in Jordanian Arabs, but the Rare Hz (GG) vs Het (AG) genetic model revealed an association of the disease with the ESR1 polymorphism rs3798577." (PMID 31888550, 2019). "ESR1 is downregulated in cancer tissues such as breast cancers, and the downregulation was shown to be associated with DNA methylation of the promoter region of ESR1." (PMID 30728052, 2019). "Hereon, we focus on the spectrum of ESR1 aberrations underlying treatment resistance and metastasis in ER+ breast cancer." (PMID 31106278, 2019).
breast cancer (continued). "These ESR1 point mutations have also been shown to drive estrogen-independent activation of ER target genes in ER+ breast cancer cells." (PMID 31106278, 2019). "While ESR1 mutations rarely occur in primary breast cancer, enrichment of ESR1 mutations is observed in metastatic breast cancer (MBC)." (PMID 31480647, 2019). "In this study genetic variations of the canine ESR1 were associated with the development of less aggressive canine mammary tumors." (PMID 31506083, 2019). "Recently, genome-wide studies have identified relationships in the expression patterns between genes and the SNPs in this region, which is upstream of the gene encoding ER (ESR1), which is associated with breast cancer susceptibility." (PMID 31237926, 2019). "In a previous study, both TAB2 and ESR1 gene polymorphisms were found to be associated with breast cancer." (PMID 31485280, 2019). "Because tamoxifen-resistant breast cancers rarely harbor ESR1 mutations, which confer only partial resistance to tamoxifen, the upstream molecular regulator of H19 in developing tamoxifen resistance remains to be investigated." (PMID 31340867, 2019). "For instance, detection of estrogen receptor 1 (ESR1) variants in ctDNA can be used for assessing possible response to endocrine therapies or resistance to aromatase inhibitor therapy in breast cancer." (PMID 31620080, 2019). "Several preclinical breast cancer models harboring ESR1 LBD point mutations have been generated, providing research platforms to characterize the functional, transcriptional, and pharmacological properties of these mutations." (PMID 31106278, 2019). "Our findings show a significant association between breast cancer and the allelic (P = 0.02486879) and genotypic (P = 0.04793066) frequencies of the ESR1 polymorphism rs3798577, a result which was confirmed in different genetic models." (PMID 31888550, 2019). "For example, loss of E-cadherin and ESR1 due to promoter hypermethylation have been reported in primary breast carcinoma cells and doxorubicin-resistant breast cancer cells and demethylation restored the expression levels of these genes." (PMID 35582717, 2019). "The ESR1 gene encodes estrogen receptor alpha, a strong candidate gene for an effect on breast cancer risk." (PMID 30642363, 2019). "To assess the effectiveness of our deconvolution, we first examined the three receptor genes associated with molecular subtypes of breast cancer: the oestrogen receptor (ESR1), progesterone receptor (PGR), and human epidermal growth factor receptor 2 (ERBB2)." (PMID 31308365, 2019). "ddPCR and next-generation sequencing have been utilized by multiple groups to detect ESR1 hotspot mutations in patients with advanced breast cancer in an appreciable frequency, and higher in the metastatic setting as compared to micrometastatic disease." (PMID 29780747, 2018). "Here, we carried out whole-exome sequencing (WES) analysis of breast cancers classified by ESR1 expression, and identified novel somatic mutations by exclusion of SNPs in the whole blood cells of patients with breast cancer." (PMID 30375428, 2018). "There are also studies evaluating the role of the ESR1 mutation in acquired endocrine resistant breast cancer." (PMID 29891002, 2018). "For this purpose, using a lentiviral vector, we inserted the cDNA encoding the mutated ESR1 (Y537S) gene into MCF7 human breast cancer cells." (PMID 30573703, 2018). "Use of an automated diagnostic platform (GeneXpert®) and assay (Xpert® Breast Cancer STRAT4) that employs RT-qPCR to quantitate ESR1, PGR, ERBB2, and MKi67 mRNAs from formalin-fixed, paraffin-embedded (FFPE) tissues facilitates analyses in less than 3 h." (PMID 30120700, 2018). "Many miRNAs that are associated with ER+/ER− breast cancer subtypes also directly target or indirectly regulate ESR1/ERα." (PMID 30214383, 2018).
breast cancer (continued). "Somatic mutations of the human estrogen receptor alpha (ESR1) have been directly implicated in the pathogenesis of hormonal therapy resistance in human breast cancer patients." (PMID 30573703, 2018). "ESR1 mutation has been studied in metastatic breast cancer, as ESR1 mutations are a very rare event in primary breast cancers with only 0.5% in a large TCGA dataset." (PMID 30305115, 2018). "There is as yet no report elucidating the relationship between somatic mutations and increased ESR1 expression in luminal subtype breast cancers, although epigenetic regulation appears to be involved in the expression of the ESR1 mRNA18." (PMID 30375428, 2018). "There is an ongoing phase II study evaluating the efficacy of fulvestrant in patients with ESR1-mutated breast cancer (NCT03202862)." (PMID 29891002, 2018). "GREB1 loss has been linked to tamoxifen resistance in ESR1+ breast cancer and cell lines; however, the effects of GREB1 expression in ESR1− cell lines have not been examined." (PMID 29973689, 2018). "In conclusion, ESR1 fusions are a new class of recurrent somatic mutations that drive endocrine therapy resistance and metastasis in ER+ breast cancer." (PMID 30525098, 2018). "(2016), who reported that ESR1 mutations were sometimes present in primary breast cancers of patients at extremely low VAFs." (PMID 29063679, 2018). "Approximately 25–40% of metastatic tumors in breast cancer patients treated with AIs show ESR1 mutations within the ligand binding domain (LBD)." (PMID 30545127, 2018). "Somatic mutation to ESR1 following prolonged estrogen-deprivation therapy represents a newly appreciated mechanism of acquired hormone resistance in metastatic breast cancer." (PMID 30489256, 2018). "Taken together, these data are consistent with ESR1 mutation representing a sub clone in a substantial fraction of patients with advanced breast cancer, poorly representing the cancer overall." (PMID 29497091, 2018). "Breast cancer is the most frequent tumor in women, and in nearly two-thirds of cases, the tumors express estrogen receptor α (ERα, encoded by ESR1)." (PMID 30375428, 2018). "We focused on the relationship between the nonsense point mutation c.2830 C>T; p.Gln944* in SIN3A and ESR1 expression in breast cancer cells, because SIN3A, which is coded by the gene for SIN3A, works as a transcriptional repressor of ERα as reported." (PMID 30375428, 2018). "Numerous groups are currently documenting molecular evolution in hormone receptor-positive disease, and current evidence indicates that ESR1 is mutated (base pair, amplification, and fusion) in up to 50% of advanced endocrine-resistant breast cancers." (PMID 29780747, 2018). "ESR1 mutant clones evolve in ER-positive advanced breast cancer during aromatase inhibitor treatment, with ESR1 mutations resulting in constitutively active ER17, 19–21." (PMID 29497091, 2018). "Recurrent point mutations clustering around the ligand binding domain (LBD) of ESR1 that cause single amino acid residue changes have been found in up to 40% of treatment-refractory, metastatic ER+ breast cancer patients (reviewed in 1)." (PMID 30525098, 2018). "The SGZ method was also applied to predict the clonality and zygosity of 12 ESR1 mutations in estrogen receptor positive breast cancer biopsies and determined these ESR1 mutations to be somatically acquired, clonal biomarkers of endocrine resistance." (PMID 29415044, 2018). "For example, hsa-miR-19b-3p regulates PTEN, a tumor suppressor that is mutated in a large number of cancers, and ESR1, mutations in which are associated with breast cancer." (PMID 29293623, 2018). "Outside of ESR1, advanced endocrine-resistant breast cancers harbor mutations in many other pathways, but again the effect of targeting these mutations is currently under investigation." (PMID 29780747, 2018). "We set out to generate the two most frequently identified ESR1 mutations Y537S and D538G in two ER+ breast cancer cell lines, T47D and MCF-7." (PMID 28535794, 2017).
breast cancer (continued). "Aromatase inhibitors inhibit breast cancer growth by estrogen deprivation and, therefore, ESR1 mutations confer resistance to aromatase inhibition because they allow tumors to proliferate independently of estrogen." (PMID 28361033, 2017). "ESR1 mutations have attracted attention as a potentially important marker and treatment target in endocrine therapy-resistant breast cancer patients." (PMID 29166868, 2017). "In our previous study, we evaluated six ESR1 mutations (K303R, S463P, Y537C, Y537N, Y537S, and D538G) in primary tumors, metastatic lesions and cfDNA of breast cancer patients." (PMID 28978004, 2017). "ESR1 mutations are relatively rare in newly diagnosed, treatment naïve breast cancer (less than 7% mutation rates in primary tumor), but appear to be frequently acquired in hormone-resistant MBC (15% - 55%)." (PMID 28978004, 2017). "Of the four independent endometriosis SNPs at this locus, the association signal for rs2206949 in intron 2 of ESR1 overlaps with the signal observed for overall breast cancer." (PMID 28537267, 2017). "Taken together, ESR1 mutations in genome-edited breast cancer cell lines confer ligand-independent growth and endocrine resistance." (PMID 28535794, 2017). "Here, we describe the generation and characterization of genome-edited T47D and MCF7 breast cancer cell lines with the two most common ESR1 mutations, Y537S and D538G." (PMID 28535794, 2017). "This review summarizes published and ongoing research covering ESR1 mutations in breast cancer, addressing epidemiological, pathophysiological issues with potential clinical implications." (PMID 28361033, 2017). "A sequence variant on ESR1 affects miRNA-binding affinity for miR-453 and the interaction is significantly associated with breast cancer risk." (PMID 28793339, 2017). "A majority of the genes corresponding to aDNAm’s were associated with cancer including breast cancer; the genes were highly enriched for ESR1 or beta-estradiol responsive genes." (PMID 29383109, 2017). "Despite the central role of the ER in luminal tumors, TCGA data for 962 breast cancer samples indicated that ESR1 mutations were present in only 0.5% of primary breast tumor cases." (PMID 28361033, 2017). "We have previously reported sensitive detection of ESR1 mutations using droplet-digital PCR (ddPCR) in 7% (3/43) primary ER-positive breast cancers, and in 24% (7/29) cfDNA samples collected from patients with recurrent disease." (PMID 28978004, 2017). "There is growing recognition that ESR1 mutations are relatively uncommon in newly diagnosed, treatment-naive breast cancer, but frequently acquired in hormone-resistant metastatic breast cancer." (PMID 28978004, 2017). "Takeshita and colleagues investigated the clinical signifcance of sequential measurements of ESR1 mutations in estrogen receptor positive breast cancer patients in a translational research." (PMID 29088906, 2017). "FGD3 mRNA is regulated by ESR1 and is associated with favorable outcome in six distinct breast cancer cohorts and four TCGA cancer cohorts." (PMID 32913979, 2017). "The deregulation of Estrogen Receptor alpha (ESR1) is a major factor causing pathogenesis of breast cancer." (PMID 29051499, 2017). "Altogether, these findings support further clinical evaluation of CDK2 inhibitors like Dinaciclib administered in combination with endocrine therapy as a potentially new treatment strategy against ESR1 mutation expressing breast cancers." (PMID 29137354, 2017). "Genetic polymorphisms altering the expression of ESR1 have been suggested to affect breast cancer susceptibility." (PMID 27825388, 2016). "Firstly, breast cancer cells with ESR1 LBD mutations can survive and breast cancer cells with ESR1 wild-type cannot survive by endocrine therapy." (PMID 27102299, 2016). "The estrogen receptor α (ESR1) gene was recently recognized as a low-penetrance breast cancer susceptibility gene." (PMID 27825388, 2016).